SOD2 (superoxide dismutase 2)
Diseases named in the same sentence as SOD2 in open-access papers (continued):
Sharing a sentence is not in itself a finding about the gene and the disease.
Infertility (15 papers, 2015 to 2025). "The SOD2 promoter SNP -262C > T “T” allele (rs4880) was recently demonstrated to be more frequent in infertile men than in the control group 135." (PMID 33806677, 2021). "Meanwhile, the infertile men with SOD2 rs4880 CC variants showed a low level of SOD activity compared with that of TT patients." (PMID 34527175, 2021). "The Ala16Val polymorphism in the SOD2 gene is associated with infertility and pregnancy rate in IVF cycles." (PMID 26618172, 2015). "In addition, other studies have associated SOD2 polymorphic expression with a significant risk for infertility, a recognized factor for testicular GCT development and with a higher degree of DNA fragmentation and 8-OHdG levels." (PMID 35205816, 2022). "Genetic variation and functional polymorphism in SOD1 and SOD2 may be associated with infertility and low IVF outcome." (PMID 34439451, 2021). "It has been showed that the presence of variant Val allele (Ala16Val polymorphism in the SOD2 gene) can alter the conformation of the secondary structure of the protein leading to decreased efficiency of transport into mitochondria which is believed to be associated with infertility." (PMID 34401649, 2021). "Supporting this, proteomic studies from the Cleveland Clinic demonstrated lower expression of mitochondrial antioxidant proteins (PRDX5 and SOD2) in idiopathic infertile men, suggesting mitochondrial oxidative damage as a key factor in IMI." (PMID 41011106, 2025). "Our results showed that SOD2 C47T was found to be significantly different among the fertile subjects (control group), infertile subjects with more than 50% motility, and infertile subjects with less than 50% motility." (PMID 34527175, 2021). "We found that four proteins (PHGPX, GSTM5, SOD2, and ATP5O) were potentially linked to infertility, neoplasia, carcinoma, and other disorders, perhaps as a consequence of oxidative stress, lipid peroxidation, apoptosis, cell proliferation, ionic homeostasis, or a combination of these processes." (PMID 27384531, 2017). "We also conclude that administering DPP in infertile males enhances the levels of expression of NRF2, GPX4, SOD2, and CAT genes and improves the semen quality including sperm count, semen volume, and morphology and motility of sperm." (PMID 34401649, 2021). "According to the findings, mRNA expression levels of antioxidant genes SOD2, GPX4, CAT and NRF2 are significantly lower in infertile case in comparison with the healthy control." (PMID 34401649, 2021). "This study was designed for investigating the mRNA expression levels of the antioxidant genes NRF2, GPX4, SOD2, and CAT in infertile males before and after treatment with DPP and healthy controls." (PMID 34401649, 2021). "Of the proteins we identified, ATP5O, PHGPX, SOD2, and GSTM5 showed significant connections to several diseases, including neoplasia, carcinoma, infertility, and others known to be related to oxidative damage, lipid peroxidation, and apoptosis." (PMID 27384531, 2017). "PRDX5 and SOD2 were significantly underexpressed, while GSR was overexpressed in the proteomics analysis, and bioinformatics indicated a general downregulation of mitochondrial activity in the infertile group." (PMID 39726694, 2024). "We could present further documents for supporting this hypothesis: altered expression of antioxidant genes NRF2, GPX4, SOD2, and CAT at mRNA levels are correlated to the greater risks of males' infertility." (PMID 34401649, 2021). "Therefore, this research aimed at the determination of the impact(s) of DPP on the levels of mRNA expression of antioxidant genes (NRF2, GPX4, SOD2, and CAT) in infertile male." (PMID 34401649, 2021).
non-small cell lung carcinoma (15 papers, 2018 to 2024). A group of at least three distinct histological types of lung cancer, including non-small cell squamous cell carcinoma, adenocarcinoma, and large cell carcinoma. "A study has shown that SOD2 can inhibit ROS production, thereby alleviating ROS-induced pyroptosis in non-small cell lung cancer." (PMID 37872948, 2023). "Downregulation of lncRNA-XIST suppressed the progression of non-small cell lung cancer (NSCLC) by triggering pyroptosis cell death mediated by miR-335/SOD2/ROS signal pathway." (PMID 35223836, 2022). "The lncRNA XIST can regulate X chromosome silent transcription and act as an miRNA sponge upregulating SOD2 to inhibit the development of non-small cell lung cancer." (PMID 34079798, 2021). "Knockdown of LncRNA-XIST inhibited non-small-cell lung cancer (NSCLC) progression by triggering pyroptosis via the miR-335/SOD2/ROS signaling pathway." (PMID 34805183, 2021). "By living within the matrix of mitochondria, members of the ferromanganese SOD2 may be able to inhibit ferroptosis in non-small cell lung cancer (NSCLC) cells prompted by mitochondrial ROS." (PMID 38515787, 2024). "Knocking down of LncRNA-XIST could inhibit pyroptosis by affecting miR-335/SOD2/ROS signal pathway in non-small cell lung cancer (NSCLC)." (PMID 35198013, 2022). "Recent studies have shown that XIST may suppress the development of non-small cell lung cancer by activating the miR-335/SOD2/ROS signaling pathway." (PMID 34804157, 2021). "It was reported that a 95% ethanolic extract prepared from the whole C. gigantea plant induced apoptotic cell death through the upregulation of ROS production by suppressing the ROS scavenger superoxide dismutase 2 and catalase in A549 and NCI-H1299 non-small cell lung cancer cells." (PMID 34343190, 2021). "The results of our study suggested that the anti-growth potential of exogenous long carbon-chain C8-ceramide against human non-small-cell lung cancer cells may occur through the modulation of the ratio of SOD1 and SOD2." (PMID 30279365, 2018).
pulmonary hypertension (15 papers, 2012 to 2023). Increased pressure within the pulmonary circulation due to lung or heart disorder. "Infusion of recombinant human ACE2 (rhACE2) in patients with pulmonary hypertension is associated with increased plasma levels of superoxide dismutase 2 (SOD2) and reduced oxidative stress." (PMID 37476705, 2023). "Infusion of recombinant human ACE2 (GSK2586881) in patients with pulmonary hypertension was associated with increased plasma levels of SOD2 and reduced oxidative stress." (PMID 33511992, 2021). "Deficiency of SOD2 aggravated CIH induced pulmonary hypertension and pulmonary vascular hypertrophy." (PMID 31915037, 2020). "Reduced SOD2 expression in pulmonary arterial smooth muscle cells of patients with pulmonary arterial hypertension (PAH) has been associated with a phenotype of increased proliferation and lower apoptosis." (PMID 31119153, 2019). "While increased DNA hypermethylation leads to suppression of genes (Sod2 and Nos3) encoding vasodilatory proteins and antioxidants in lungs of hypoxic mice, pulmonary artery SMCs of fawn‐hooded rats, and endothelial cells of fetal lamb with pulmonary hypertension." (PMID 35581740, 2022). "In pulmonary arterial hypertension, DNA methylation has a key function in modulating the expression of superoxide dismutase 2 (SOD2), a major antioxidant protein enzyme localized in mitochondria." (PMID 35052850, 2022). "Our study showed that knockdown of SOD2 increased pulmonary hypertension and vascular muscularization." (PMID 31915037, 2020). "CIH induced down-regulating of SOD2 increased pulmonary hypertension and vascular muscularization." (PMID 31915037, 2020). "Similarly, in a mouse model of bleomycin-induced pulmonary hypertension, recombinant ACE2 treatment increased pulmonary SOD2 expression, reduced oxidative stress and attenuated development of vascular remodelling." (PMID 33511992, 2021). "Furthermore, fawn-hooded rats, which have an epigenetic silencing of SOD2 expression/activity, and SOD1 knockout mice develop spontaneous pulmonary hypertension." (PMID 28666030, 2017). "Two hypothesis-driven studies have already demonstrated methylation alterations in the genes coding for the superoxide dismutase 2 (SOD2) and granulysin in pulmonary hypertension (PH)." (PMID 28881789, 2017). "The superoxide dismutase 2 (SOD2) gene is a pivotal part of oxidative stress system, which could induce the onset of pulmonary arterial hypertension (PAH)." (PMID 28272301, 2017). "Accumulating evidence has suggested that impaired activity of SOD2 and SOD3 contributed to pulmonary hypertension, and the level and activity of SOD1 has not been found significantly changed in human pulmonary hypertension." (PMID 33947399, 2021).
lung adenocarcinoma (14 papers, 2013 to 2024). A carcinoma that arises from the lung and is characterized by the presence of malignant glandular epithelial cells. "However, it is unclear whether tumor-associated inflammation mediates SOD-2 to contribute to cell invasion in AFG1-induced lung adenocarcinoma." (PMID 28801561, 2017). "In terms of carcinogenesis, it was found that the increase in SOD2 expression in mouse lung adenocarcinoma induced by Aflatoxin G1 (AFG1) was related to the upregulation of Vimentin, α-SMA, Twist1, and MMP." (PMID 37759978, 2023). "Our results showed that miR-335 was downregulated in either NSCLC tissues or cell lines comparing to the Control group, which was negatively correlated with LncRNA-XIST and SOD2 and in line with the Pan-cancer analysis in lung adenocarcinoma." (PMID 31553952, 2019). "The results indicate that increased SOD-2 is associated with tumor progression and migration in AFG1-induced lung adenocarcinoma." (PMID 28801561, 2017). "The expression of TNF-α, IL-6, and macrophage marker CD68, as well as E-cadherin, vimentin, Twist, matrix metalloproteinase (MMP)-2, MMP-9, and SOD-2 were examined in AFG1-induced lung adenocarcinoma." (PMID 28801561, 2017). "SOD-2 expression was significantly upregulated in AFG1-induced lung adenocarcinoma compared to that in control lung tissues." (PMID 28801561, 2017). "Western blot results further indicated that SOD-2 was upregulated in the lung tissues of AFG1-induced lung adenocarcinoma mice." (PMID 28801561, 2017). "Here, we found increased SOD-2 expression associated with vimentin, α-SMA, Twist1, and MMP upregulation in AFG1-induced lung adenocarcinoma." (PMID 28801561, 2017). "In this study, we collected the lung tissues from AFG1-induced lung adenocarcinoma mice, and found increased SOD-2 expression in AFG1-induced lung adenocarcinoma." (PMID 28801561, 2017). "It has been shown that SOD2+/−Gpx1−/− mice develop lymphoma and lung adenocarcinomas in advanced age." (PMID 27221200, 2016). "SOD2+/−Gpx1−/−mice has increased incidents of tumorigenesis, but the tumors are primarily lymphoma and to a lesser degree lung adenocarcinoma." (PMID 27221200, 2016). "In contrast, SOD2 (Superoxide Dismutase 2, Mitochondrial) induces the activation of NF-κB and increases IKKβ transcription in lung adenocarcinoma." (PMID 27234396, 2013). "Therefore, TNF-α-mediated lung inflammation can upregulate SOD2 expression in lung adenocarcinoma, and macrophages contribute to SOD2 upregulation by secreting TNF-α." (PMID 34777635, 2021). "The aim of the present study was to investigate whether AFG1-induced tumor-associated inflammation mediates SOD-2 upregulation to contribute to EMT and cancer cell invasion in AFG1-induced lung adenocarcinoma." (PMID 28801561, 2017). "If AFG1 induces tumor-associated inflammatory responses, there is a critical need to identify whether the tumor-associated inflammation mediates SOD-2 upregulation to contribute to EMT and migration in AFG1-induced lung adenocarcinoma." (PMID 28801561, 2017). "Those cells work together to produce pro-inflammatory and inflammatory cytokines, which may maintain an inflammatory environment to mediate SOD-2 upregulation in AFG1-induced lung adenocarcinoma." (PMID 28801561, 2017). "Those cytokines may contribute to AFG1-induced inflammatory responses as well as SOD-2 upregulation in AFG1-induced lung adenocarcinoma." (PMID 28801561, 2017). "Thus, the role of SOD-2 upregulation in AFG1-induced lung adenocarcinoma is unclear." (PMID 28801561, 2017). "Thus, we suggest that tumor-associated inflammation mediates SOD-2 upregulation through NF-κB pathway, which may contribute to EMT and cell migration in AFG1-induced lung adenocarcinoma.Introduction." (PMID 28801561, 2017).
lung adenocarcinoma (continued). "Before the initiation of AFG1-induced lung adenocarcinoma, we also reported that AFG1-induced chronic inflammation may cause alveolar epithelial oxidative stress evidenced by the increase of manganese superoxide dismutase (SOD-2) expression." (PMID 28801561, 2017). "To further investigate the relation between SOD-2 overexpression and EMT, we examined the well-defined markers of EMT, including E-cadherin, vimentin, α-SMA, and Twist1 in AFG1-induced lung adenocarcinoma." (PMID 28801561, 2017). "We identified alterations in genes involved in chromatin remodeling (PBRM1, SETD2), oxidative stress (CUL3, SOD2), immune response (CSMD3, SYK), and gamma-aminobutyric acid receptor signaling (GABRD, GABRG1) in lung adenocarcinoma." (PMID 24576404, 2014). "Thus, it can be considered that SOD1, SOD2, or SOD3 play an important role in colorectal cancer, lung adenocarcinoma, and other cancers." (PMID 37759978, 2023). "In summary, we found that erlotinib-resistant lung adenocarcinoma cells depended on ALDH1A1 and that ALDH1A1 conferred EMT and drug resistance by facilitating the ROS-RCS metabolic pathway and by activating GPX4 and SOD2 transcription." (PMID 31695757, 2019). "The results indicate that SOD-2 may significantly favor inflammation-mediated EMT and migration of tumor cells in AFG1-induced lung adenocarcinoma." (PMID 28801561, 2017). "All above results suggest that SOD-2 upregulation upon inflammation responses may contribute to TNF-α-mediated EMT and migration in tumor cells in AFG1-induced lung adenocarcinoma." (PMID 28801561, 2017). "Thus, the inflammation-mediated SOD-2 through NF-κB pathway plays an important role in EMT and migration in tumor cells in AFG1-induced lung adenocarcinoma, which suggests a new mechanism of AFG1-induced lung carcinogenesis." (PMID 28801561, 2017). "Whether SOD-2 contributes to the migration and invasion of AFG1-induced lung adenocarcinoma is unknown." (PMID 28801561, 2017). "Immunohistochemical results showed diffused strong positive SOD-2 expressions in cytoplasm could be seen in AFG1-induced lung adenocarcinoma cells, while negative or weak staining of SOD-2 was observed in normal lung tissues." (PMID 28801561, 2017).
autism (13 papers, 2014 to 2025). Persistent deficits in social interaction and communication and interaction as well as a markedly restricted repertoire of activity and interest as well as repetitive patterns of behavior. "Alterations in SOD2 enzyme function have been associated with different neurobiological disorders as well as with autism." (PMID 31018497, 2019). "Maternal diabetes–mediated oxidative stress is diminished due to hematopoietic stem cells transplantation with increased Sod2 expression, apart from triggering epigenetic changes in neurons, thereby impairing autism-like behavior in autism-like offspring." (PMID 41245836, 2025). "Maternal diabetes induced autism-like behavior through hyperglycemia-mediated sustained oxidative stress and inhibition of SOD2." (PMID 37759978, 2023). "In a separate study, it was confirmed that maternal diabetes inhibited SOD2 expression while exacerbating autism in offspring induced by oxidative stress in mice." (PMID 37759978, 2023). "Maternal diabetes-induced mouse offspring were established as the experimental autistic model, and we found that they showed significant autism-like behavior and neuronal SOD2 suppression compared to the control group." (PMID 33101089, 2020). "We have previously found that prenatal progestin exposure-induces autism-like behavior in offspring through ERβ/SOD2 suppression in neurons." (PMID 33101089, 2020). "Our results indicate that expression of ERβ/SOD2 in the amygdala plays an important role in autism-like behavior." (PMID 33101089, 2020). "In autism postmortem brains, the Thalamus region-specific present alteration with SOD2 gene shows upregulated expression." (PMID 31018497, 2019). "In fact, we have previously reported that prenatal progestin exposure induces suppression of ERβ and SOD2 in the amygdala and results in reactive oxygen species (ROS) formation and mitochondrial dysfunction, subsequently triggering autism-like behavior." (PMID 31685635, 2019). "We showed that maternal diabetes-induced autism-like behavior is restored by SOD2 expression in the amygdala." (PMID 31685635, 2019). "Maternal diabetes induces autism-like behavior in offspring with SOD2 suppression in the amygdala in rats, while SOD2 overexpression in the amygdala ameliorates autism-like behavior." (PMID 31685635, 2019). "Maternal diabetes induces persistent oxidative stress and triggers epigenetic changes with histone methylation at H3K9me2 on the SOD2 promoter, subsequently resulting in SOD2 suppression with related embryo damage and autism-like behavior in offspring." (PMID 31685635, 2019). "Overexpression of SOD2 partly restores this effect, indicating that SOD2 expression plays an important role in autism-like behavior." (PMID 31685635, 2019). "Maternal diabetes induces autism-like behavior in offspring, with suppressed expression of SOD2 and ERβ in the amygdala." (PMID 31685635, 2019). "SOD2 overexpression in the amygdala ameliorates autism-like behavior, while prenatal treatment of antioxidants MnTBAP and RSV partly prevents, and postnatal treatment of RSV partly restores, this effect." (PMID 31685635, 2019). "The in vivo rat experiments showed that maternal T1D-induced autism-like behavior (ALB) in offspring can be restored by SOD2 overexpression in the amygdala." (PMID 31685635, 2019). "Our results indicate that maternal diabetes-induced autism-like behavior can be partly restored by postnatal expression of SOD2 in the amygdala." (PMID 31685635, 2019). "Maternal diabetes–induced autism-like behaviors and social deficits in offspring are attributed to SOD2 suppression owing to OS-mediated histone methylation and the subsequent dissociation of early growth response 1 (Egr1) from the SOD2 promoter." (PMID 41511288, 2025). "Furthermore, we have recently showed that maternal diabetes induces autism-like behavior through epigenetic changes on the SOD2 promoter with subsequent SOD2 suppression in the amygdala." (PMID 33101089, 2020).